BIRC8 (baculoviral IAP repeat containing 8)
Description:
Protects against apoptosis mediated by BAX.
Synonyms: ILP-2; hILP2; RNF136
Gene: Transcribed processed pseudogene on chromosome 19 (53,289,664 to 53,291,131, reverse strand). Ensembl gene ENSG00000163098.
Subcellular location: Cytoplasm
Diseases named in the same sentence as BIRC8 in open-access papers:
BIRC8 is named in the same sentence as 6 diseases in open-access papers, as found by Europe PMC text mining. Sharing a sentence is not in itself a finding about the gene and the disease. The quoted sentences say what the papers report.
colorectal cancer (1 paper, 2020). A primary or metastatic malignant neoplasm that affects the colon or rectum. "Online databases Oncomine and GEPIA were used to compare the expression of IAPs (NAIP, BIRC2, BIRC3, XIAP, BIRC5/survivin, BIRC6 and BIRC7, no data on BIRC8 was available) between colorectal cancer and normal tissues." (PMID 32381104, 2020).
tumor (3 papers, 2021 to 2024). "Seven IAP family genes (except BIRC8) exhibited elevated mRNA levels in the tumour stage 1–4 subgroups relative to normal tissue, according to the findings." (PMID 38364254, 2024). "We observed that the BIRC2, BIRC3, BIRC5, and BIRC7 genes showed the increased levels of expression in tumor tissue compared to normal tissue, while in the case of the BIRC1, BIRC4, BIRC6, and BIRC8 genes, we saw the decreased expression levels." (PMID 33673050, 2021). "We discovered that the mRNA levels of all IAP family members were upregulated in HNSCC compared to those in non-tumour cells, but BIRC8 was not statistically significant." (PMID 38364254, 2024).
cancer (2 papers, 2018 to 2021). A tumor composed of atypical neoplastic, often pleomorphic cells that invade other tissues. "In addition, both BIRC4 and BIRC8 belong to the inhibitor of apoptosis (IAP) family of proteins, which are altered in many types of human cancer, and are known to regulate caspases and apoptosis, inflammatory signaling and immunity, mitogenic kinase signaling, proliferation and mitosis." (PMID 29433439, 2018).
BIRC8 also shares sentences with these, for which no sentence is quoted: melanoma (2 papers); keratoconus (1); nasopharyngeal carcinoma (1).